NABP2 (nucleic acid binding protein 2)
Description:
Component of the SOSS complex, a multiprotein complex that functions downstream of the MRN complex to promote DNA repair and G2/M checkpoint. In the SOSS complex, acts as a sensor of single-stranded DNA that binds to single-stranded DNA, in particular to polypyrimidines. The SOSS complex associates with DNA lesions and influences diverse endpoints in the cellular DNA damage response including cell-cycle checkpoint activation, recombinational repair and maintenance of genomic stability. Required for efficient homologous recombination-dependent repair of double-strand breaks (DSBs) and ATM-dependent signaling pathways.
Synonyms: SOSS-B1; hSSB1; OBFC2B; SSB1; MGC2731
Tractability: PROTAC: UniProt records ubiquitination sites on it; ubiquitination databases record sites on it.
Gene: Protein-coding gene on chromosome 12 (56,222,000 to 56,229,859, forward strand). Ensembl gene ENSG00000139579.
Subcellular location: Nucleus
Subcellular location (Human Protein Atlas): Nucleoplasm
Pathways (Reactome):
Gene expression (Transcription): RNA polymerase II transcribes snRNA genes
Gene Ontology:
Molecular function: C-rich strand telomeric DNA binding; DNA polymerase binding; G-rich strand telomeric DNA binding; protein binding; single-stranded DNA binding; DNA binding
Biological process: DNA damage response; DNA repair; double-strand break repair via homologous recombination; establishment of protein localization to telomere; mitotic G2/M transition checkpoint; positive regulation of telomere capping; response to ionizing radiation
Cellular component: chromosome, telomeric region; nucleoplasm; nucleus; site of double-strand break; SOSS complex
Genetic constraint (gnomAD): Loss-of-function variants: 7 observed, 23.97 expected, observed/expected ratio (o/e) 0.29, 90% interval 0.17 to 0.55. The upper end of that interval is the gene's LOEUF score, 0.55, which puts it in group 2 of 6, group 1 being the genes least tolerant of losing a copy. Missense variants: 184 observed, 274.98 expected, observed/expected ratio (o/e) 0.67, 90% interval 0.59 to 0.76. Synonymous variants: 106 observed, 102.32 expected, observed/expected ratio (o/e) 1.04, 90% interval 0.88 to 1.22.
Homologues: Orthologues: chimpanzee NABP2 (100% identical), macaque NABP2 (99% identical), pig NABP2 (96% identical), dog NABP2 (96% identical), rabbit NABP2 (95% identical), guinea pig NABP2 (94% identical), mouse Nabp2 (93% identical), rat Nabp2 (83% identical), tropical clawed frog nabp2 (71% identical), zebrafish nabp2 (63% identical). Paralogues in human: NABP1 (55% identical).
Diseases named in the same sentence as NABP2 in open-access papers:
NABP2 is named in the same sentence as 10 diseases in open-access papers, as found by Europe PMC text mining. Sharing a sentence is not in itself a finding about the gene and the disease. The quoted sentences say what the papers report.
diabetes (2 papers, 2015 to 2025). "In a GWAS study of the Taiwan Biobank (TWB), four novel genes—NABP2, RASA2, RNF41, and SLC39A5—were identified for human height, and it was also discovered that these genes have associated with cardiovascular disease, diabetes, and cancer." (PMID 39910149, 2025).
NABP2 also shares sentences with these, for which no sentence is quoted: cancer (10 papers); tumor (5); prostate carcinoma (2); cardiovascular disease (1); dementia (1); insulin dependent diabetes mellitus (1); Miller-Dieker syndrome (1); osteosarcoma (1); prostate tumors (1).